CXorf38 (chromosome X open reading frame 38)
Synonyms: MGC39350
Tractability: PROTAC: ubiquitination databases record sites on it; its protein half-life has been measured.
Gene: Protein-coding gene on chromosome X (40,626,921 to 40,647,569, reverse strand). Ensembl gene ENSG00000185753.
Subcellular location (Human Protein Atlas): Cytosol; Vesicles
Gene Ontology:
Molecular function: protein binding
Cellular component: mitochondrion
Homologues: Orthologues: chimpanzee CXHXorf38 (99% identical), macaque CXHXorf38 (98% identical), pig CXorf38 (88% identical), dog CXorf38 (88% identical), guinea pig CXorf38 (88% identical), mouse 1810030O07Rik (86% identical), rat Cxhxorf38 (85% identical), rabbit CXorf38 (76% identical), tropical clawed frog c2hxorf38 (46% identical), zebrafish si:ch211-91p5.3 (28% identical).
Diseases named in the same sentence as CXorf38 in open-access papers:
CXorf38 is named in the same sentence as 7 diseases in open-access papers, as found by Europe PMC text mining. Sharing a sentence is not in itself a finding about the gene and the disease. The quoted sentences say what the papers report.
lung adenocarcinoma (1 paper, 2025). A carcinoma that arises from the lung and is characterized by the presence of malignant glandular epithelial cells. "Cell proliferation and colony formation assays were used to examine the function of CXorf38 by overexpressing the gene in lung adenocarcinoma cell lines." (PMID 40559995, 2025). "To conclude, our study provides the first functional characterization of CXorf38 in lung adenocarcinoma, highlighting its potential as a tumor suppressor and prognostic biomarker." (PMID 40559995, 2025). "Given that ZIP8 regulates essential micronutrients linked to diseases including cancer, this study aims to characterize CXorf38 and evaluate its role in lung adenocarcinoma." (PMID 40559995, 2025). "Higher CXorf38 expression correlated with improved survival in patients with lung adenocarcinoma, but not in lung squamous cell carcinoma." (PMID 40559995, 2025).
lung carcinoma (1 paper, 2025). "Kaplan–Meier survival analysis was used to assess the prognostic value of CXorf38, while TCGA clinical database analysis was used to evaluate its expression in lung cancer tissues, particularly in smokers." (PMID 40559995, 2025). "In this study, we aim to elucidate the biological function of CXorf38 and investigate its potential role in lung cancer." (PMID 40559995, 2025). "Bioinformatics analyses (GO, KEGG, PPI, and ICI) were performed on CXorf38-coexpressed genes derived from patients with lung cancer." (PMID 40559995, 2025). "Clinical data showed CXorf38 downregulation with lung cancer tissues of smokers, indicating a potential role in smoking-induced cancer progression and treatment." (PMID 40559995, 2025).
malnutrition (1 paper, 2022). Inadequate nutrition resulting from poor diet, malabsorption, or abnormal nutrient distribution. "In particular, the differentially expressed proteins (e.g., C9orf85 and CXorf38) identified in the ZIP8-KO cells could be potential targets for diagnosing and/or treating a wide range of human ZIP8-associated diseases, including but not limited to malnutrition, viral infection, and cancers." (PMID 36330220, 2022).
cancer (2 papers, 2022 to 2025). A tumor composed of atypical neoplastic, often pleomorphic cells that invade other tissues. "Specifically, CXorf38 was significantly co-expressed with ZIP8 in 18 out of 40 cancer types, whereas C9orf85 was only in nine out of 40 cancer types." (PMID 36330220, 2022). "Furthermore, clinical-based bioinformatic analysis indicated that positive correlations between the gene expressions of ZIP8 and C9orf85 or CXorf38 were observed in multiple cancer types." (PMID 36330220, 2022). "In addition, we performed clinical-based bioinformatic analysis to evaluate the potential connections between the gene expressions of ZIP8 and C9orf85 or CXorf38 in multiple cancer types." (PMID 36330220, 2022).
tumor (1 paper, 2025). "Functional analysis using bioinformatics linked CXorf38 to immune response regulation, suggesting involvement in the tumor immune microenvironment." (PMID 40559995, 2025). "Furthermore, bioinformatics analysis indicates that CXorf38 could be involved in tumor immune regulation." (PMID 40559995, 2025).
CXorf38 also shares sentences with these, for which no sentence is quoted: lung squamous cell carcinoma (1 paper); viral infection (1).